SIRT1 (sirtuin 1)
Diseases named in the same sentence as SIRT1 in open-access papers (continued):
Sharing a sentence is not in itself a finding about the gene and the disease.
tumor (continued). "Both SIRT1 and ALDH1 expression was significantly suppressed by either silenced SIRT1 or overexpressed miR-34a in tumor tissues." (PMID 25826085, 2015). "In this paper, keratinocyte-specific heterozygous deletion of SIRT1 enhanced tumorigenesis, whereas homozygous deletion of this gene inhibited tumor development." (PMID 26437418, 2015). "In tumor cells, SIRT1 appeared predominantly in the nucleus of the cells whereas SIRT2 was located mainly in the cytoplasm." (PMID 25915617, 2015). "The results showed that, compared to the control cells, the tumor volume of the SIRT1-overexpressing cells with long term repeated exposure to B[a]P was significantly larger." (PMID 26318035, 2015). "Further in line with tumor-promotive function, SIRT1 stimulated constitutive Wnt signaling and Wnt-induced cell migration in the colon cancer cell lines HT-29, HCT116, RKO and DLD-1." (PMID 26437418, 2015). "Taken together, these results indicate that SIRT1 is also involved in tumor growth prompted by G-1 in vivo." (PMID 26225773, 2015). "Further, due to established roles of SIRT1 in influencing life span for calorie restriction and senescence in tumor cell growth, we determined the effects of miR-212 in modulating cellular senescence." (PMID 26439987, 2015). "In this review, we have highlighted reports on SIRT1-mediated regulation of processes involved in lipid metabolism and homeostasis and discuss the implications for tumor biology." (PMID 25569080, 2015). "A role of SIRT1 in tumorigenesis is still controversial because this protein has been shown to act as both tumor suppressor and tumor promoter." (PMID 26437418, 2015). "SIRT1 can serve as a tumor promoter or tumor suppressor, depending on the oncogenic pathway specific to particular tumors." (PMID 24892674, 2014). "Western blotting showed that SIRT1 high expression related with statistics to advanced tumor progression, positive lymphatic invasion, positive venous invasion, and advanced stage but not to poor prognosis." (PMID 25146318, 2014). "A low differentiation grade was found in 21% of patients with low expression of LSD1, HDAC2 and SIRT1 and 43% of the patients with high expression of all three enzymes had a low grade of tumor differentiation." (PMID 25139823, 2014). "Statistical analysis was then preformed to investigate the relevance of SIRT1 expression and various clinicopathologic features and to examine the effect of SIRT1 on tumor-induced lymphangiogenesis, LVI and prognosis." (PMID 25922660, 2014). "In parallel experiments, we found that SIRT1 overexpression promoted tumor growth in an injectable mouse model." (PMID 25522783, 2014). "We uncovered a key role for SIRT1 as a tumor promoter that enhances invasive and metastatic potential in HCC using HCC cell models." (PMID 25522783, 2014). "Univariate analysis revealed the value of LVD, LVI and SIRT1 in prognosing tumor relapse and poor OS." (PMID 25922660, 2014).
tumor (continued). "Resveratrol had little effect on tumor formation except in animals heterozygous for the mutant Sirt1 gene." (PMID 25380034, 2014). "When the combined expression levels were analyzed, high expression of LSD1, HDAC2 and SIRT1 showed shorter patient survival time and shorter time to tumor relapse and correlated with poor tumor differentiation and a high level of tumor cell proliferation." (PMID 25139823, 2014). "In HNSCC, both SIRT1 and DBC1 expressions were associated with tumor regression and a favorable prognosis, despite a dissociation between transcriptional and translational levels." (PMID 25146318, 2014). "We found that 15 pairs of matched normal and tumor tissue samples obtained from 21 OSCC patients showed significantly higher SIRT1 expression in the normal tissue as compared to the tumor tissue." (PMID 25424420, 2014). "The effect of Sirt1 expression in tumor tissues on the outcome of these patients was also investigated." (PMID 24959282, 2014). "The roles of SIRT1 in tumor cell migration/invasion and metastasis to the lungs were investigated using the Boyden chamber assay and orthotopic injections, respectively." (PMID 25424420, 2014). "In summary, the collaborations among LDHA, MYC and SIRT1 can indeed widen the window of miR-34-induced tumor suppression." (PMID 24884974, 2014). "Some sirtuins, such as SIRT2 and SIRT6, seem to function as tumor suppressors, but others, such as SIRT1, are apparently bifunctional, operating as both tumor suppressors and oncogenic factors, depending on cellular context and study conditions." (PMID 25486244, 2014). "Previous studies have indicated that Sirt1 is considered to play the part of a tumor promoter and tumor suppressor in tumorigenesis." (PMID 24959282, 2014). "SIRT1 was recently found to be overexpressed and/or catalytically activated in tumor cells, suggesting that SIRT1 acts as a tumor promoter." (PMID 25216517, 2014). "A clinicopathological analysis showed that SIRT1 expression was significantly correlated with tumor size, tumor number, and TNM staging." (PMID 25522783, 2014). "The role of SIRT1 is however somewhat puzzling, acting both as a tumor suppressor or tumor promoter." (PMID 24742694, 2014). "In summary, there are correlations between the combined expression levels of LSD1, HDAC2 and SIRT1 and tumor differentiation and between the combined expression levels of these enzymes and tumor cell proliferation." (PMID 25139823, 2014). "Percentages of positive nuclei for LSD1, HDAC2 and SIRT1 in the tumor and normal tissue cores were determined by IHC." (PMID 25139823, 2014). "Resveratrol has been reported to reduce the incidence of tumor formation and, in at least some cases, this effect is dependent on the SIRT1 protein." (PMID 25380034, 2014). "By associating and deacetylating Smad4, SIRT1 enzyme can influence MMP7 expression, MMP enzyme activity, and consequently, cell migration, invasion, and tumor metastasis in OSCCs." (PMID 25424420, 2014).
tumor (continued). "It should be noted that the mechanisms of tumor lymphangiogenesis and lymphatic metastasis are exceptionally complex, and the exact role of SIRT1 protein in lymphangiogenesis and lymphatic metastasis remains to be further studied." (PMID 25922660, 2014). "By contrast, some tumor tissues showed Sirt1-positive stained cells clustered in certain areas of the tissue, and the ratio of stained cells in such tissue samples was >80%." (PMID 24959282, 2014). "SIRT1 also functions in the regulation of metabolism and maintaining the integrity of the genome, and has thus been described as a potential tumor suppressor." (PMID 25486244, 2014). "The results showed that the expression levels of LSD1 and SIRT1 were increased in tumor tissues compared to adjacent normal breast tissues." (PMID 25139823, 2014). "In the context of the expression of Foxp3 in the tumor infiltrating lymphocytes, it is likely that the SIRT1 effects a reduction in the suppressive function of these T regulatory cells which is likely to be reversed by vorinostat." (PMID 24395633, 2014). "First, in tumor cells, SIRT1 localizes to the promoters of TSGs, including E-cadherin, SFRPs, MLH1, and p27, that are aberrantly hypermethylated, leading to their transcriptional repression and subsequent unregulated cell proliferation." (PMID 25146318, 2014). "Previously we showed that SIRT1 expression is upregulated in a subset of HCC, and its overexpression is associated with more advance tumor grades." (PMID 24416313, 2014). "The present study was designed to determine the effects of SIRT1 in tumor cells subjected to antitumor agent treatment and to identify the underlying mechanisms during the stress response." (PMID 24137378, 2013). "When analyzed with regard to the morphological features and tumor extent, the expression of Sirt1 was significantly correlated to poor histological differentiation (p = 0.001)." (PMID 24088390, 2013). "There was a lag in tumor latency that modestly extended survival in Sirt1 mutant mice that we attribute to a delay in mammary gland development and not to a direct effect of SIRT1 on carcinogenesis." (PMID 24278473, 2013). "Another study reported that SIRT1 haplo-insufficiency promotes tumorigenesis in mice, implying that SIRT1 is a tumor suppressor." (PMID 23460888, 2013). "SIRT1 is upregulated in several tumor types and can inhibit apoptosis and downregulate the expression of tumor suppressor genes to impact epithelial cancer cells." (PMID 23819063, 2013). "Sirt1 was expressed by tumor cells with varying degrees of nuclear atypia, forming either neoplastic duct like structures, solid masses or single cell infiltrates within desmoplastic stroma." (PMID 24088390, 2013). "The invivo tumorgenesis and metastasis assays showed that SIRT1 knockdown dramatically reduced the tumor volume and the metastatic ability in nude mice." (PMID 24223900, 2013). "The authors also identified CDK6, SIRT1 and Sp1 as miR-22 targets and postulated that miR-22 act as tumor suppressor." (PMID 22538858, 2013). "Our results indicate that SIRT1 acts as a tumor promoter in the APC+/min mouse model of intestinal tumorigenesis." (PMID 23799088, 2013). "This phenotype is congruent with one previously reported for systemic SIRT1 knockout animals, which showed that tumor size is significantly decreased upon SIRT1 inactivation, whereas the total number of intestinal polyps remained the same." (PMID 23799088, 2013). "It is PTEN’s tumor suppressive quality that sets it apart from other recent studied genes such as SIRT1." (PMID 28548055, 2013).
tumor (continued). "The in vivo tumorgenesis assay showed that nude mice inoculated subcutaneously with SIRT1 si-RNA-transfected cells had markedly reduced tumor volume compared to mice received cells transfected with control si-RNA transfection (730±141vs." (PMID 24223900, 2013). "Class III histone deacetylase SIRT1 blocks senescence and apoptosis and promotes cell growth and angiogenesis, making it a critical regulator of tumor initiation, prognosis and drug resistance." (PMID 23768087, 2013). "Taken together, our findings indicate that SIRT1 plays a tumor-promoting role in the mouse intestinal tumor model." (PMID 23799088, 2013). "There are several reports indicating that SIRT1 is involved in processes thought to be important for tumor progression and metastases." (PMID 24278473, 2013). "At protein level, the expression of SIRT1 was significantly correlated with the tumor clinical stage (P = 0.005) and lymph node metastasis (P = 0.021)." (PMID 23805287, 2013). "Our study has shown that SIRT1 acts primarily as a tumor promoting factor in hepatocellular carcinogenesis." (PMID 23024800, 2012). "In the present study, we demonstrate that the expression of SIRT1 and c-Myc are positively correlated and both promote the proliferation of tumor cells." (PMID 23024800, 2012). "Further study beyond the scope of this work is warranted to further define the precise tumor promoting mechanism provided by SIRT1." (PMID 23024800, 2012). "Overall, independent of MYC, the deacetylation mediated inhibition of several tumor suppressors including FoxO3, Rb, and Ku70, together suggest that SIRT1 has significant tumor promoting activity." (PMID 23024800, 2012). "Our lab has reported that resveratrol suppresses tumor growth by inducing apoptosis in tumor cells through aryl hydrocarbon receptor (AhR) and by reciprocal regulation of SIRT1 and NF-κB signaling." (PMID 22532866, 2012). "Conversely, a tumor suppressive role for SIRT1 is suggested by a reciprocal transcriptional control mechanism between c-Myc and SIRT1." (PMID 23024800, 2012). "In contrast, tumor growth in the SIRT1 H363Y transgenic mice was reduced and was similar to that observed in the wild-type mice." (PMID 23028940, 2012). "Endothelial cells were successfully isolated from the LLC xenografts of SIRT1 transgenic mice using CD31-conjugated magnetic beads as well as a series of steps to remove all contaminating tumor cells and leukocytes." (PMID 23028940, 2012). "To determine the function of DLL4 during tumor angiogenesis in the SIRT1 transgenic mice, we decreased the DLL4 level present in a murine tumor model using an anti-DLL4 monoclonal antibody." (PMID 23028940, 2012). "It is therefore likely that SIRT1 can function either as an oncogene or tumour suppressor, depending on SIRT1 targets in the cellular context, with the dominant target determining the outcome." (PMID 21698133, 2011). "In tumor cells, Sirt1 acts as a negative regulator of NF-κB, that represents a master regulator of inflammatory signalling." (PMID 21931678, 2011). "In tumor cells, Sirt1 is located in the promoter of densely hypermethylated tumor suppressor genes (E-cadherin, MLH1, GATA-4, GATA-5 and p27) and contributes to their transcriptionally inactive state." (PMID 21307403, 2011).
tumor (continued). "On the other hand, SIRT1 can be pro-apoptotic and anti-proliferative, and consequently has been proposed to behave as a tumor suppressor in vivo." (PMID 18414679, 2008). "This study addresses this controversial question by testing the effects of SIRT1 on tumor formation and growth." (PMID 18414679, 2008). "In summary, using biochemistry, mouse genetics, and clinical tumor specimens we have found that SIRT1, a diet-responsive gene, is a regulator of β-catenin and has a tumor suppressive function." (PMID 18414679, 2008). "While CR is known to inhibit both spontaneous and induced tumor formation, a role for SIRT1 in this process remains to be demonstrated." (PMID 18414679, 2008). "Nevertheless, our data provide in vivo evidence that overexpression of SIRT1 at physiologically relevant levels, can suppress tumor formation and growth." (PMID 18414679, 2008). "Since the tumor suppressive effects mediated by SIRT1 eclipse those seen by CR (70% reduction (SIRT1) versus 40% reduction (CR)) we cannot exclude the possibility that SIRT1 also inhibits tumor growth by a CR-independent mechanism." (PMID 18414679, 2008). "Furthermore, evidence of the stage-dependent dual role of SIRT1, tumor suppression in early lesions, and oncogenicity in advanced disease, remains underexplored." (PMID 41008982, 2025). "The results suggest that the activation of the NAD+ salvage pathway and SIRT1 by CANA might promote tumor growth, which is consistent with those of previous studies reporting that SIRT1 suppression inhibits CCA growth." (PMID 39940750, 2025). "Understanding the differential roles of cytoplasmic and nuclear SIRT1 in tumor pathophysiology could also open avenues for targeted therapies to improve patient outcomes by modulating SIRT1 localization and activity." (PMID 39858444, 2025). "In addition, other studies have also reported that SIRT1 can participate in tumor immune escape, drug resistance, and inhibition of CRC through miRNA." (PMID 40567502, 2025). "HIC1 hypermethylation reduces its tumor expression, significantly upregulating SIRT1." (PMID 41208649, 2025). "SIRT1 contributes to hormone-driven tumor growth by enhancing ERα-mediated transcription." (PMID 41300302, 2025). "Furthermore, targeting the PI3K signaling pathway suppressed tumor growth and significantly downregulated the miR-155-5p/SIRT1 axis within the tumors." (PMID 41281644, 2025). "In GC cells treated with oxaliplatin in xenograft tumor mouse model, SIRT1 may modulate chemotherapy resistance by influencing ferroptosis." (PMID 40567502, 2025). "In contrast, other research suggests that SIRT1 activation may suppress tumor progression in TNBC in certain contexts." (PMID 41300302, 2025).